PNPLA1 (patatin like domain 1, omega-hydroxyceramide transacylase )
Description:
Omega-hydroxyceramide transacylase involved in the synthesis of omega-O-acylceramides (esterified omega-hydroxyacyl-sphingosine; EOS), which are extremely hydrophobic lipids involved in skin barrier formation. Catalyzes the last step of the synthesis of omega-O-acylceramides by transferring linoleic acid from triglycerides to an omega-hydroxyceramide. Omega-O-acylceramides, are required for the biogenesis of lipid lamellae in the stratum corneum and the formation of the cornified lipid envelope which are essential for the epidermis barrier function. These lipids also play a role in keratinocyte differentiation (By similarity). May also act on omega-hydroxylated ultra-long chain fatty acids (omega-OH ULCFA) and acylglucosylceramides (GlcEOS) (By similarity).
Synonyms: FLJ38755; dJ50J22.1; ARCI10
Tractability: No criterion of Open Targets' tractability assessment is met for any kind of drug.
Gene: Protein-coding gene on chromosome 6 (36,243,203 to 36,313,955, forward strand). Ensembl gene ENSG00000180316.
Subcellular location: Cytoplasm
Gene Ontology:
Molecular function: acyltransferase activity, transferring groups other than amino-acyl groups; omega-hydroxyceramide transacylase activity; structural constituent of skin epidermis; triacylglycerol lipase activity; hydrolase activity
Biological process: ceramide biosynthetic process; omega-hydroxyceramide biosynthetic process; lipid homeostasis; triglyceride catabolic process; lipid catabolic process; lipid metabolic process
Cellular component: cytoplasm; lipid droplet; membrane
Genetic constraint (gnomAD): Loss-of-function variants: 33 observed, 46.68 expected, observed/expected ratio (o/e) 0.71, 90% interval 0.54 to 0.94. The upper end of that interval is the gene's LOEUF score, 0.94, which puts it in group 4 of 6, group 1 being the genes least tolerant of losing a copy. Missense variants: 615 observed, 663.65 expected, observed/expected ratio (o/e) 0.93, 90% interval 0.87 to 0.99. Synonymous variants: 273 observed, 276.73 expected, observed/expected ratio (o/e) 0.99, 90% interval 0.89 to 1.09.
Homologues: Orthologues: chimpanzee PNPLA1 (92% identical), macaque PNPLA1 (90% identical), dog PNPLA1 (78% identical), rabbit PNPLA1 (75% identical), mouse Pnpla1 (62% identical), pig PNPLA1 (62% identical), guinea pig PNPLA1 (61% identical), rat Pnpla1 (60% identical). Paralogues in human: PNPLA2 (25% identical), PNPLA5 (21% identical), PNPLA3 (21% identical), PNPLA4 (14% identical).
Diseases named in the same sentence as PNPLA1 in open-access papers:
PNPLA1 is named in the same sentence as 19 diseases in open-access papers, as found by Europe PMC text mining. Sharing a sentence is not in itself a finding about the gene and the disease. The quoted sentences say what the papers report.
ichthyosis (22 papers, 2014 to 2026). Disorders of cornification that are characterized by visible scaling and/or hyperkeratosis of most or all of the skin. "For example, it was shown that ABHD5 can also activate PNPLA1, and that mutations in PNPLA1 lead to LD accumulation and ichthyosis, similar to mutations in ABHD5." (PMID 40275410, 2025). "Mutations in PNPLA1 or alpha-beta-hydrolase domain containing five (ABHD5) are responsible for congenital ichthyosis in golden retrievers, in which a common insertion-deletion mutation in PNPLA1 appears to have been spread by in-breeding." (PMID 37087101, 2023). "For example, mutations in the gene encoding patatin-like phospholipase domain-containing 1 (PNPLA1), which plays a pivotal role in the biosynthesis of acylceramide, cause autosomal recessive congenital ichthyosis." (PMID 36639058, 2023). "Further revealing the molecular mechanism of ichthyosis caused by PNPLA1 mutations will thus provide new strategies to treat patients with skin barrier defects in the future." (PMID 35893253, 2022). "Various pure and compound heterozygous mutations in the PNPLA1 gene have been identified from a registry of human ichthyosis patients." (PMID 35893253, 2022). "In 2012, two homozygous mutations in the human PNPLA1 gene were identified in ichthyosis patients for the first time." (PMID 35893253, 2022). "Consistent with the predominant expression of PNPLA1 in the granular layer and its strong upregulation during keratinocyte differentiation, the authors found that mutations in PNPLA1 are associated with the pathogenesis of ichthyosis in humans and dogs." (PMID 36355098, 2022). "Following this initial report, several other research groups identified PNPLA1 mutations in humans linked to ichthyosis pathogenesis." (PMID 36355098, 2022). "Another significant issue is the unreliability of the PNPLA1 mutation in prediction of clinical manifestation of ichthyosis." (PMID 29738490, 2018). "Ichthyosis in Golden Retrievers was suggested to be an autosomal recessive disorder caused by a variant in the PNPLA1 gene." (PMID 29738490, 2018). "Although it has been unclear why PNPLA1 mutations cause ichthyosis, our results suggest that decreases in acylceramide levels are the cause of skin barrier defects and lead to ichthyosis." (PMID 28248318, 2017). "In addition to humans, several mutations in the PNPLA1 gene were also demonstrated to be linked to dog ichthyosis." (PMID 35893253, 2022). "In addition, a genetic study summarizing the localization of previously known PNPLA1 mutations in ichthyosis patients concluded that PNPLA1, like ATGL, requires a larger region than the core patatin domain to exert its full enzymatic activity." (PMID 36355098, 2022). "Furthermore, the reliability of the PNPLA1 mutation in prediction of clinical signs of ichthyosis is unclear." (PMID 29738490, 2018). "Thus, our findings provide important insights into the molecular mechanism of acylceramide production and into the function and pathogenic role of the ichthyosis-causative gene PNPLA1." (PMID 28248318, 2017). "In Golden Retrievers lamellar ichthyosis was shown to be associated with a mutant PNPLA1 (patatin-like phospholipase domain containing 1) which was supposed to harbor potential causative mutations for human ichthyosis in European and North African populations as well." (PMID 26506231, 2015). "The typical features of severe ichthyosis, including the extensive loss of the highly organized lipid lamella structure in the SC, abnormal secretion of lamellar granule contents at the SG–SC interface, and unusual lipid aggregates within corneocytes, were observed in Pnpla1-knockout mice." (PMID 35893253, 2022). "In 2017, three laboratories independently reached the same conclusion from Pnpla1-deficient mice that PNPLA1 is essential for epidermal acylceramide biosynthesis, and that the decrease in or absence of acylceramide biosynthesis impaired the barrier function of the skin and led to ichthyosis." (PMID 35893253, 2022).
ichthyosis (continued). "Overall, these findings confirm that PNPLA1-related ichthyosis remains one of the most prevalent hereditary disorders in Golden Retrievers, although its frequency is decreasing." (PMID 41875098, 2026). "Given the importance of acylCers in maintaining skin barrier integrity, especially in the context of ichthyosis, we aimed to investigate how mutations in ABHD5 affect the protein's ability to stimulate PNPLA1." (PMID 40818613, 2025). "In dogs, at least six different breed-specific ichthyoses including a relatively common PNPLA1-related autosomal recessive ichthyosis in Golden Retrievers are known." (PMID 34791225, 2022). "ICH2 cases tend to have more keratinocytes with perinuclear clear spaces than dogs with the PNPLA1-related ichthyosis." (PMID 34791225, 2022). "The clinical and histological presentation of ICH2-affected dogs strongly resembled that of the well-known PNPLA1-related ichthyosis in Golden Retrievers." (PMID 34791225, 2022). "Mutations in the genes coding for patatin-like phospholipase domain-containing 1 (PNPLA1) and α/β-hydrolase domain-containing 5 (ABHD5), also known as comparative gene identification 58, are causative for ichthyosis, a severe skin barrier disorder." (PMID 30361410, 2018). "Additional studies are needed to investigate if PNPLA1 is the only gene involved or if other genes and environmental factors have a role in the development of ichthyosis in Golden Retrievers." (PMID 29738490, 2018). "Next, we directly measured the transacylase activities of the ichthyosis mutants of PNPLA1 in vitro." (PMID 28248318, 2017). "Disease-associated amino acid substitutions in ABHD5 disrupt either its interaction with PNPLA1 or its localization to LDs, both of which ultimately impair PNPLA1 recruitment/localization and its enzymatic function, thereby leading to the pathogenesis of ichthyosis." (PMID 40818613, 2025). "In this study, we investigated 14 Golden Retrievers with scales that were not homozygous for the mutant PNPLA1 allele suggesting a genetically distinct new form of ichthyosis." (PMID 34791225, 2022). "Histologically, the epidermis in ICH2-affected dogs is thicker than in dogs with the PNPLA1-related ichthyosis dogs and this may correspond with a more severe barrier defect." (PMID 34791225, 2022). "In addition, the essential role of PNPLA1-mediated acylceramide in ACRI and the interaction of PNPLA1 with ABHD5 provided clues to elucidate the mechanisms of ichthyosis symptoms in Chanarin–Dorfman syndrome." (PMID 35893253, 2022). "Despite the phenotypic similarity to the PNPLA1-related ichthyosis, none of these dogs carried the mutant PNPLA1 allele in a homozygous state." (PMID 34791225, 2022). "A non-epidermolytic ichthyosis has been identified in Golden Retrievers due to a variant in the PNPLA1 gene, and a genetic test is available to detect wild-type, heterozygous and homozygous dogs." (PMID 29738490, 2018). "Conversely, alleles of ABHD5 carrying point mutations associated with ichthyosis in humans failed to accelerate PNPLA1-mediated AcylCer biosynthesis." (PMID 30361410, 2018). "Altogether, our results indicate that PNPLA1 is directly involved in acylceramide synthesis as a transacylase, and provide important insights into the molecular mechanisms of skin barrier formation and of ichthyosis pathogenesis." (PMID 28248318, 2017). "Recently, a study demonstrated homozygous puppies could exhibit clinical signs suggestive of ichthyosis prior to 1 year of age and become subclinical in adulthood suggesting that the PNPLA1 genotype is more closely correlated with the clinical phenotype at a young age than in adulthood." (PMID 29738490, 2018). "In Golden Retrievers, non-epidermolytic ichthyosis is associated with variants in the PNPLA1 gene." (PMID 29738490, 2018).
ichthyosis (continued). "The enzymatic activity of PNPLA1 is enhanced by ABHD5, which may present triglycerides to PNPLA1 to facilitate substrate recognition, providing a mechanism whereby ABHD5 mutations cause Chanarin-Dorfman syndrome accompanied by ichthyosis with impaired ω-O-acylceramide formation." (PMID 33086624, 2020). "Most well documented forms of canine ichthyosis are non-epidermolytic, involving genetic variants in ABHD5 or PNPLA1 in golden retrievers, TGM1 in Jack Russell terriers, NIPAL4 in American bulldogs, and ASPRV1 in a German shepherd dog." (PMID 36251712, 2022). "Accordingly, humans carrying mutant alleles of ELOVL4, CYP4F22, or CERS3 develop a similar ichthyosis pathology as reported for ABHD5 and PNPLA1 deficiency due to the lack of ULC ω-hydroxy ceramides and AcylCer in the epidermis." (PMID 30361410, 2018). "Mutant forms of PNPLA1 found in patients with ichthyosis exhibit reduced or no enzyme activity in either cell-based or in vitro assays." (PMID 28248318, 2017). "The transacylase activities of the ichthyosis PNPLA1 mutants were reduced or not detected in vitro." (PMID 35893253, 2022).
autosomal recessive congenital ichthyosis (9 papers, 2014 to 2025). Autosomal recessive form of inherited ichthyosis. "Loss-of-function mutations in patatin-like phospholipase domain-containing protein 1 (PNPLA1) cause autosomal recessive congenital ichthyosis, and altered PNPLA1 activity is implicated in the pathogenesis of atopic dermatitis and other common skin diseases." (PMID 37087101, 2023). "In humans, biallelic loss-of-function mutations in PNPLA1 cause autosomal recessive congenital ichthyosis, a rare genetic disease with lifelong barrier dysfunction and generalized scaly and inflamed skin." (PMID 37087101, 2023). "In recent years, more and more mutations of the PNPLA1 gene have been found to be linked to autosomal-recessive congenital ichthyosis (ARCI)." (PMID 35893253, 2022). "The function of patatin-like phospholipase domain-containing protein 1 (PNPLA1) was a mystery until the finding that PNPLA1 gene mutations were involved in autosomal-recessive congenital ichthyosis (ARCI) patients, both humans and dogs." (PMID 35893253, 2022). "Based on clinical examination and genetic testing, a diagnosis of SICB was confirmed, with mutations identified in genes commonly associated with autosomal recessive congenital ichthyosis, such as ALOX12B, TGM1, ALOXE3, CYP4F22, and PNPLA1." (PMID 40193669, 2025).
Obesity (2 papers, 2009 to 2018). Accumulation of substantial excess body fat. "Logistic regression identified six variants in PNPLA1 that show association with obesity when adjusting for age and gender (rs9380559, rs12212459, rs1467912, rs4713951, rs10947600 and the coding rs12199580)." (PMID 19390624, 2009). "Obesity-associated variants in PNPLA1 and PNPLA3 and the association with phenotypes using multiple regression analyses." (PMID 19390624, 2009). "Six variants in PNPLA1 showed association with obesity (rs9380559, rs12212459, rs1467912, rs4713951, rs10947600, and rs12199580, p<0.05 after adjustment for age and gender)." (PMID 19390624, 2009). "We did find a modest effect of PNPLA1 on obesity and PNPLA3 on insulin sensitivity although these data need confirmatory studies." (PMID 19390624, 2009). "Genetic variants in PNPLA1 and PNPLA3 showing significant association with obesity using logistic regression." (PMID 19390624, 2009). "We found borderline association with obesity for PNPLA1 and PNPLA3, but these data would not hold for multiple corrections." (PMID 19390624, 2009). "PNPLA1 exhibited a modest effect on obesity and PNPLA3 on insulin sensitivity." (PMID 19390624, 2009). "Furthermore, PLAGL1 may be implicated in lipid metabolism and obesity through its effect on IDI1, PNPLA1, JAK3, and RAB37 expression." (PMID 30082726, 2018).
cervical cancer (1 paper, 2023). A primary or metastatic malignant neoplasm involving the cervix. "PNPLA1 is associated with lipid metabolism, and its nonsense mutation has been identified in human cervical cancer HeLa cells." (PMID 35789548, 2023).
infection (1 paper, 2017). The state of being infected such as from the introduction of a foreign agent such as serum, vaccine, antigenic substance or organism. "Infection with a lentivirus bearing the shRNA specific for PNPLA1 (shPNPLA1) caused a large decrease in PNPLA1 mRNA levels compared with the control." (PMID 28248318, 2017).
PNPLA1 also shares sentences with these, for which no sentence is quoted: autosomal recessive congenital ichthyosis 10 (3 papers); congenital ichthyosis (3); Ataxia (2); Chanarin-Dorfman syndrome (2); Cone rod dystrophy (2); atopic dermatitis (1); Brain atrophy (1); cancer (1); cone-rod dystrophy 2 (1); inflammatory bowel disease (1); Myokymia (1); paraplegia (1); pustular psoriasis (1); retinitis pigmentosa (1).